HDAC3 (histone deacetylase 3)
Diseases named in the same sentence as HDAC3 in open-access papers (continued):
Sharing a sentence is not in itself a finding about the gene and the disease.
diabetes (continued). "RGFP966, as a specific inhibitor for HDAC3, is more promising for the treatment of diabetes complicated with ischemic stroke." (PMID 30906786, 2019). "By using HDAC3 knockout mice and highly selective HDAC3 inhibitor, increasing evidence support that HDAC3 is involved in the pathophysiology of diabetes mellitus and many neurological disorders." (PMID 31101061, 2019). "Our study demonstrated that HDAC3 inhibitor RGFP966 is a potential drug target for the treatment of diabetes complicated with ischemic stroke." (PMID 30906786, 2019). "Separately, activity of the Class I HDAC, HDAC3 was found to be significantly increased in the hearts of Type 1 diabetic OVE26 mice, whereas selective HDAC3 inhibition improved diabetes-induced cardiac dysfunction." (PMID 29934664, 2018). "In fact, accumulating literature favors inhibition of HDAC3 as a potential strategy for developing novel diabetes therapeutics." (PMID 27904654, 2016). "Nevertheless, after STZ treatment, the histological islet β-cell mass decreased dramatically in HDAC3 KO mice, in consistent with their dramatically increased blood glucose level and diabetes incidence." (PMID 27542279, 2016). "Islet morphology, insulin secretion, glucose tolerance, and multiple low-dose streptozotocin (STZ)-induced diabetes incidence were evaluated and compared between HDAC3 knockout and wild type littermate controls." (PMID 27542279, 2016). "Consistent with different blood glucose levels, 60% of the HDAC3 KO mice, while only 20% from WT controls developed diabetes by day15." (PMID 27542279, 2016). "Under high-fat diets, the absence of HDAC3 leads to heart failure and is associated with congenital defects and damage to the heart in diabetes." (PMID 40660005, 2025). "Previous study has demonstrated that Hdac3-specific inhibitor MS-275 protects β-cells against cytokine-induced apoptosis in type 1 diabetes, as well as from palmitate-induced cell death in diabetes." (PMID 39580381, 2024). "This notion is supported by the finding of histone deacetylase 3 (HDAC3) as the most significantly altered epigenetic regulator in atherosclerotic lesion’s macrophages in human patients with diabetes and the attenuation of atherosclerotic plaques with depletion of HDAC3 in mice models." (PMID 39796562, 2024). "However, more studies are required to uncover the different roles of HDAC3 in type 1 and type 2 diabetes mellitus." (PMID 34301918, 2021). "Therefore, in this study, we explored the mechanism by which the HDAC3-mediated Rev-erbα/BMAL1 pathway increases MI/RI vulnerability in diabetes and its relationship with mitophagy rhythm." (PMID 33414413, 2021). "Finally, cardiac-specific HDAC3 knockdown restored diabetes-induced vulnerability to MI/RI, and silencing of HDAC3 showed beneficial effects against diabetic MI/RI." (PMID 33414413, 2021). "However, the mechanism by which the HDAC3-orchestrated Rev-erbα/BMAL1 pathway increases MI/RI in diabetes and its relationship with mitophagy have yet to be elucidated." (PMID 33414413, 2021). "Growing evidences indicated that HDAC3 is related to diabetes and the complications, including diabetic liver lesions, diabetic aortic atherosclerosis, diabetic osteoporosis, diabetic cardiomyopathy, diabetic cerebral ischemia reperfusion model, and diabetic nephropathy model." (PMID 32190700, 2020). "Together, these results showed that MS-275 improved inflammation and insulin resistance in skeletal muscle, principally by inhibiting HDAC3, and may thus be a promising candidate treatment for obesity and diabetes-related insulin resistance." (PMID 33362555, 2020). "Together, these results showed that MS-275 induced HDAC3 inhibition in skeletal muscle and may represent a promising candidate treatment for obesity and diabetes-related insulin resistance." (PMID 33362555, 2020). "It is believed that HDAC3 may become a potential drug target for the treatment of diabetes complicated with ischemic stroke." (PMID 30906786, 2019).
diabetes (continued). "But evidences suggest that selective inhibition of HDAC3 may be an attractive strategy for targeting diabetes and may increase the resistance of the central nervous system to ischemic injury." (PMID 30906786, 2019). "HDAC3 inhibition protected against diabetes-induced BBB permeability." (PMID 31101061, 2019). "Evidences suggested that effective inhibition of HDAC3 may help to prevent or treat either ischemic stroke or diabetes, respectively." (PMID 30906786, 2019). "It is prospective that HDAC3 inhibition may be a potential drug target for the treatment of diabetes complicated with ischemic stroke." (PMID 30906786, 2019). "In this study, we found that HDAC3 inhibition may protect against diabetes-induced BBB damage through Nrf2 activation." (PMID 31101061, 2019). "Histone deacetylase 3 (HDAC3) has been recently identified as a potential target for the treatment of cancer and other diseases, such as chronic inflammation, neurodegenerative diseases, and diabetes." (PMID 28106794, 2017). "Mice with β-cell-specific HDAC3 deletion displayed decreased pancreatic insulin content, disrupted glucose-stimulated insulin secretion, with intermittent spontaneous diabetes and dramatically enhanced susceptibility to STZ-induced diabetes." (PMID 27542279, 2016). "Mice with β-cell-specific HDAC3 deletion displayed decreased insulin content, disrupted glucose-stimulated insulin secretion and tolerance, and dramatically enhanced susceptibility to low dose STZ induced diabetes." (PMID 27542279, 2016). "To conclude, in a relevant clinical diabetes setting, we have demonstrated increased HDAC3 activity/HDAC3 mRNA levels in patients with type 2 diabetes that was positively correlated to all the inflammatory markers profiled, poor glycemic control, and insulin resistance." (PMID 27904654, 2016). "By day25, more than 80% of HDAC3 KO mice, while only about 27% from WT controls developed diabetes." (PMID 27542279, 2016). "Elucidating the connectionsbetween DBC1, HDAC3 and Rev-erbs may have implications for the pathogenesis and treatment ofmetabolic diseases such as obesity, diabetes, liver steatosis and metabolic syndrome." (PMID 23398316, 2013). "Therefore, pharmacological inhibition of HDAC3 may serve as a novel therapeutic strategy to treat patients with diabetes mellitus." (PMID 34301918, 2021). "Treatment with a selective HDAC3 inhibitor also reduces hyperglycemia and increases insulin secretion in type-2 diabetes in mice, which indicates that HDAC3 may be a potential target for the therapy of diabetes." (PMID 29498635, 2018). "In the mitochondria, HDAC3 facilitated HADHA deacetylation and induced aberrant mitochondrial FAO and injury, contributing to cardiac insult in diabetes." (PMID 40052435, 2025). "HDAC3 worsens post-MI remodelling via MMP activation and compromised autophagy, particularly in diabetes." (PMID 40660005, 2025). "And combined HDAC3 and HDAC9 genes with diabetes mellitus worsen atherosclerosis and resulted in stroke." (PMID 34301918, 2021). "HDAC3 inhibition using RGFP966 mitigated diabetes-induced inflammation, aortic fibrosis, and pathological liver injury in mice with type 1 diabetes mellitus." (PMID 34301918, 2021). "We observed that HDAC3, Caspase3, and LC3B expressions augmented along with the diabetes duration in RGCs of db/db mice." (PMID 32190700, 2020). "However, it is unclear whether HDAC3 plays an important role in diabetes complicated with stroke." (PMID 30906786, 2019). "Histone deacetylase 3 (HDAC3), a member of the HDAC family, is expressed in almost all human tissues, including the brain, and has been reported to be upregulated in diabetes and cerebral ischemic stroke." (PMID 30906786, 2019). "Histone deacetylase 3 (HDAC3) is a potential target for the treatment of human diseases such as cancers, diabetes, chronic inflammation and neurodegenerative diseases." (PMID 29464997, 2018).
diabetes (continued). "Histone deacetylase 3 (HDAC3) activity is significantly increased in diabetic mice’s hearts, and inhibiting these enzymes blocks the inflammation and oxidative stress driven by diabetes, enhancing cardiac remodeling and mitigating mouse dysfunction." (PMID 40100371, 2025). "RGFP966, a specific HDAC3 enzymatic inhibitor, significantly reduced diabetic cardiomyopathy (DCM), as evidenced by reduced diabetes-induced cardiac dysfunction, hypertrophy, and fibrosis and decreased cardiac oxidative stress, inflammation, and insulin resistance." (PMID 37674539, 2023). "MS-275, a nonspecific inhibitor of HDAC1 and HDAC3, potentiated insulin secretion in the islets of rats with type 2 diabetes mellitus." (PMID 34301918, 2021). "We therefore not only, in this study, assessed HDAC3 mRNA, protein, and activity using brain hippocampus and cortex tissues, but also tested our hypothesis in cultured HBMEC under in vitro diabetes condition and hyperglycemia plus IL-1β exposure." (PMID 31101061, 2019). "In diabetes models, BRD3308 can inhibit the synthesis and secretion of inflammatory factors and reduce pancreatic β-cell apoptosis via selective inhibition of HDAC3.In addition, several selective HDAC3 inhibitors derived from natural compounds have also been found." (PMID 37072432, 2023). "Experiments have shown that mice with pancreatic β‐cells lacking Hdac3 displayed decreased pancreatic insulin content and disrupted glucose‐stimulated insulin secretion, with intermittent spontaneous diabetes and enhanced susceptibility to STZ‐induced diabetes." (PMID 34984701, 2022). "In a mouse model of type 2 diabetes mellitus (T2DM), HDAC3 activity, but not protein expression, was found to be increased in endothelial cells." (PMID 39050859, 2024).
hepatocellular carcinoma (33 papers, 2012 to 2025). A malignant tumor that arises from hepatocytes. "Further in line with our findings, up-regulation of HDAC3 was strongly associated with the down-regulation of miR-195 in hepatocellular carcinoma cells." (PMID 33549119, 2021). "We have previously shown that HDAC1, HDAC2, and HDAC3 (HDAC1–3) genes encoding histone deacetylases 1–3 are upregulated in primary human hepatocellular carcinoma (HCC)." (PMID 27342975, 2016). "Loss of HDAC3 could lead to hepatocellular carcinoma, while another study found that the increased HDAC3 levels are associated with improved patient survival." (PMID 34973135, 2023). "This is in accord with previous studies showing upregulation of MYC in hepatocellular carcinoma through dissociating K63-ubiquitinated HDAC3 from the MYC promoter." (PMID 40305047, 2025). "For instance, HDAC3 ubiquitination by the E3 ligase TRAF6 leads to MYC upregulation in hepatocellular carcinoma due to dissociation of K63-ubiquitinated HDAC3 from the MYC promoter." (PMID 40305047, 2025). "HDAC-3 overexpression has been found to correlate with shorter survival rates in gastric, hepatocellular carcinoma and glioblastoma, whereas it has been associated with prolonged survival in primary and stage IV metastatic melanoma cases." (PMID 33799478, 2021). "In this work, 20 out of 20 HDAC3−/− displayed low grade hepatocellular carcinoma at a mean age of 10.2 months." (PMID 22559741, 2012). "For example, Shehawy demonstrated that the strong interaction between the herbal active ingredients Thymoquinone and Piperine with DNMT3B and HDAC3 inhibited the activity of hepatocellular carcinoma cells and led to growth arrest and cell death by molecular docking." (PMID 40406241, 2025). "In hepatocellular carcinoma cells, TRAF6 has oncogenic potential by interacting with and ubiquitinating HDAC3 with K63-linked ubiquitin chains, which leads to the dissociation of HDAC3 from the c-Myc promoter." (PMID 38609495, 2024). "Similarly, depleted HDAC3 is believed to inhibit hepatocyte proliferation in hepatocellular carcinoma." (PMID 33203425, 2020). "This raises the question whether, in liver, Hdac3 exhibits increased protein stability as it has been suggested that its absence leads to hepatocellular carcinoma and disrupted lipid and cholesterol homeostasis in mice." (PMID 29951776, 2018). "Notably, HDAC3 has been suggested to induce the reduction of microRNA-195-5p (miR-195-5p) in hepatocellular carcinoma, which may suggest the role of miRNA biogenesis in malignant cells." (PMID 36266728, 2022). "Finally, while highly speculative, it is interesting to note that the liver specific deletion of HDAC3 results in hepatocellular carcinoma in mice." (PMID 22559741, 2012). "This identifies HDAC3 as a lineage-specific ferroptosis regulator in CRC, contrasting with its pro-ferroptotic role reported in other cancer types such as hepatocellular carcinoma or glioblastoma." (PMID 40947430, 2025). "In hepatocellular carcinoma, the majority of lactylation sites exhibit positive correlations with HDAC1-3, and knockdown of HDAC3 in HepG2 cells leads to an increase in lactylation intensity." (PMID 38711083, 2024). "Kcr expression was also downregulated in HCC, correlating with the TNM stage, while HDAC1 and HDAC3 simultaneous knockdown or HDACi trichostatin A (TSA) treatment improved the Kcr level, coincidently limiting hepatoma cell motility and proliferation." (PMID 38315203, 2024). "In a mouse kidney transplantation model and hepatocellular carcinoma (HCC), the inhibition of HDAC3 can maintain MMP and reduce mitochondria-related apoptosis." (PMID 37072432, 2023). "As described in advance, the HDAC3 inhibitor, RGFP966 plays an inhibitory actor for tumor growth in hepatocellular carcinoma." (PMID 33203425, 2020).
hepatocellular carcinoma (continued). "Histone deacetylase 3 (HDAC3) plays pivotal roles in cell cycle regulation and is often aberrantly expressed in various cancers including hepatocellular carcinoma (HCC), but little is known about its role in liver regeneration and liver cancer cells proliferation." (PMID 29540666, 2018). "On the contrary, our data shows direct interactions among FOXO1, HDAC3, and HDAC4 in HepG2 which is a well-differentiated hepatocellular carcinoma of humans." (PMID 30424007, 2018). "In addition, during TGF-β-initiated EMT, the effect of TGF-β on Snail2 expression is related to the inhibition of HDAC1 and HDAC3, which can suppress Snail2 transcription by downregulating the acetylation levels of H3K56 and H3K4 in hepatocellular carcinoma (HCC) cells." (PMID 35484625, 2022). "Previously, we found that ZBP-89 could bind to histone deacetylase 3 (HDAC3) protein to inhibit its deacetylation activity, leading to the increase of pro-apoptotic Bak protein expression in hepatocellular carcinoma (HCC)." (PMID 25623232, 2015).
Obesity (32 papers, 2013 to 2025). Accumulation of substantial excess body fat. "Any deficiencies or dysregulations of NCoR1, NCoR2, and HDAC3 have been associated with metabolic diseases such as obesity, type 2 diabetes, and NAFLD." (PMID 37674539, 2023). "What are the precise molecular mechanisms causing HDAC3/NCoR1 corepressor complex dysregulation in metabolic diseases such as type 2 diabetes, obesity and cardiovascular disease?" (PMID 37674539, 2023). "In parallel, mice with intestinal HDAC3 deletion show a pronounced reduction in adiposity and are particularly resistant to high-fat diet-induced obesity, which is further associated with improved glycaemic control." (PMID 31757939, 2019). "Taken together, these results suggest that HDAC3 may be implicated the development of obesity and T2D." (PMID 35145486, 2021). "In addition, Hdac3 can integrate microbiota-derived signals to control intestinal homeostasis in intestinal epithelial cells (IECs), where disruption of Hdac3 causes weight loss and improves metabolic profile, suppressing the diet-induced obesity." (PMID 33240312, 2020). "Previous studies suggested the roles of HDACs as key epigenetic players in obesity development and we observed a higher expression of Hdac3 per cell as well as a higher number of cells expressing Hdac3 in mLFD group (Padj < 0.001, mHFD vs mLFD)." (PMID 38493217, 2024). "Overall, our studies demonstrate that Hdac3 deletion enhances intramembranous bone healing in a setting of diet‐induced obesity, possibly through increased production of CCL2 by macrophages within the defect." (PMID 39261913, 2024). "DBC1 is involved in cellular senescence during obesity by inhibiting histone deacetylase 3 (HDAC3), driving inflammatory responses." (PMID 36291773, 2022). "In obesity, inactivation of HDAC3 increases or decreases the expression of different genes related to lipidogenesis and fatty acid and lipid oxidation." (PMID 34829943, 2021). "The present and former findings indicated that PEITC reduces obesity-induced inflammation by inhibiting HDAC3." (PMID 33261070, 2020). "Microbiota-derived BA decreases the weights of mice with HFD induced obesity by weakening the activity of epithelial HDAC3." (PMID 32334588, 2020). "It affects the thermogenesis of brown adipocytes via an interaction with HDAC3 (Histone deacetylase 3); this phenomenon has promising implications for the treatment of obesity." (PMID 32854233, 2020). "Here we demonstrate that intestine-specific deletion of Hdac3 (Hdac3IKO) protects mice from diet induced obesity." (PMID 31757939, 2019). "Many studies have also concluded HDAC3 as an emerging target for inflammation, insulin-resistance, and type 2 diabetes which are closely related to obesity." (PMID 30126161, 2018). "An intriguing observation in this study is that RORα is crucial to recruit HDAC3 to repress hepatic PPARγ-mediated lipogenic genes and protect against diet-induced hepatic steatosis and obesity." (PMID 28757615, 2017). "HDAC3 inhibits PPARγ and nuclear transcription factor-κB (NF-κB), and HDAC3 inhibition restores PPARγ function in obesity." (PMID 29258184, 2017). "Dysregulation of this HDAC3 and NCoR1/2 complex can contribute to the development of metabolic syndrome, a cluster of interconnected metabolic abnormalities, including insulin resistance, dyslipidemia, and obesity." (PMID 37674539, 2023). "In addition, SCFAs can also prevent diet-induced obesity by inhibiting the activity of Histone Deacetylase 3 in intestinal epithelial cells." (PMID 36733799, 2022). "After combining these pieces of evidence, it should be clear that butyrate could inhibit HDAC3 in IECs, and thereby reduced the activity of diet-induced obesity." (PMID 34203243, 2021). "HDAC3 also co-activated Estrogen-Related Receptor α (ERRα), inducing microbiota-dependent rhythmic transcription of the lipid transporter gene Cd36 and promoting lipid absorption and dietary-induced obesity." (PMID 32106534, 2020).